STMN1 (stathmin 1)
Diseases named in the same sentence as STMN1 in open-access papers (continued):
Sharing a sentence is not in itself a finding about the gene and the disease.
osteosarcoma (14 papers, 2015 to 2024). A usually aggressive malignant bone-forming mesenchymal neoplasm, predominantly affecting adolescents and young adults. "To investigate the effect of the loss of interaction between p27 and STMN1 on the mobility of osteosarcoma cells, we used HOS and 143B cell lines expressing either recombinant wt or T198A mutant protein to perform migration and invasion assays." (PMID 30992462, 2019). "For another example, miR‐423‐5p overexpression inhibits osteosarcoma cell metastasis by inhibiting STMN1 expression." (PMID 33174687, 2020). "Our data also suggest the interaction of STMN1 with cytoplasmic p27 stabilizes the microtubule cytoskeleton and promotes osteosarcoma cell migration." (PMID 30992462, 2019). "Our results show that T198 phosphorylation of p27 controls the interaction between p27 and STMN1 that regulates microtubule stabilization and the invasion and migration of osteosarcoma cells." (PMID 30992462, 2019). "Collectively, our data revealed that T198 phosphorylation regulates p27 activity through the interaction with STMN1 that stabilizes the microtubule cytoskeleton and promotes osteosarcoma cell migration." (PMID 30992462, 2019). "Two proteins were increased (GLO1, CTSD) and the other two were decreased (RANBP1, STMN1) in osteosarcomas and metastases based on the 2-DE expression profile." (PMID 26203049, 2015). "By contrast, miR-423-5p had significantly low expression in osteosarcoma tissues, and miR-423-5p expression could suppress osteosarcoma cell proliferation, colony formation, and invasion ability by targeting STMN1 expression." (PMID 33924142, 2021). "Interestingly, previous studies reported that miR-1247 targeting neuroplilin 1 and neuroplilin 2 in pancreatic cancer, targeting MAP3K9 in osteosarcoma, and targeting STMN1 in NSCLC, thereby regulated tumor cells proliferation." (PMID 29793538, 2018). "Since our present findings associate cytoplasmic p27 localization with the metastatic potential of osteosarcoma cells, we evaluated the mRNA levels of the set of metastatic markers, VIM, SNA2, CDH2, CTNNB1 and STMN1 following XPO1 inhibition and AZD1775 exposure, by RT-qPCR." (PMID 30992462, 2019).
non-small cell lung carcinoma (12 papers, 2012 to 2025). A group of at least three distinct histological types of lung cancer, including non-small cell squamous cell carcinoma, adenocarcinoma, and large cell carcinoma. "In multiple cancers, including non-small cell lung cancer, STMN1 is abnormally expressed at high levels and promotes tumor cell proliferation by influencing microtubule stability and regulating phosphorylation levels." (PMID 40963874, 2025). "STMN1 promotes cell differentiation, proliferation, and migration, and it is increased in numerous malignancies, including non-small cell lung cancer, breast cancer, and gastric cancer." (PMID 36127700, 2022). "The AKT/FOXM1/STMN1 pathway was indicated to drive resistance to tyrosine kinase inhibitors in advanced non-small cell lung cancer including LSCC." (PMID 32993587, 2020). "In sarcoma cells and non-small cell lung cancer, STMN1 stimulated cell motility in and through the extracellular matrix in vitro and increased the metastatic potential in vivo." (PMID 22470493, 2012). "Furthermore, STMN1 overexpression is associated with upregulation of FOXM1 in patients with advanced non-small cell lung cancer, and STMN1/FOXM1 upregulation leads to poor prognosis." (PMID 36127700, 2022).
gallbladder cancer (10 papers, 2016 to 2024). "Under glucose deficiency conditions, the hKIS/p27/E2F1 axis regulates STMN1 expression and gallbladder carcinoma cell migration and invasion." (PMID 35186166, 2022). "The downregulation of STMN1 has been observed to impede the growth of gallbladder cancer cells and mitigate the Warburg effect." (PMID 38317842, 2024). "Wang and colleagues showed that the invasion of PCa reduced by silencing of STMN1 in gallbladder cancer; however, they used miRNA 34a for STMN1 inhibition in their study." (PMID 37529254, 2022). "STMN1 knockdown inhibited the migration and invasion of gallbladder cancer cells induced by the MUC16 C-terminal polypeptide." (PMID 35186166, 2022). "In gallbladder cancer progression, miR-223 targeted STMN1 mRNA and regulated its expression and inhibited cell growth." (PMID 34489401, 2021). "Several published researches have reported that STMN1 is overexpressed in various human cancers, including gallbladder carcinoma." (PMID 29312550, 2017). "MiR-223 regulates STMN1 expression to modulate cell growth and metastasis in gallbladder cancer." (PMID 31827394, 2019). "Besides, xenografted gallbladder carcinoma cells growth were significantly impaired after STMN1 was silenced in vivo." (PMID 27349455, 2016). "Abnormal expression of Stathmin 1(STMN1) plays an important role in the proliferation and migration of gallbladder carcinoma (GBC)." (PMID 29312550, 2017).
lymph node metastasis (10 papers, 2012 to 2022). "High expression levels of stathmin 1 have been associated with lymph node metastasis and increased malignancy in oesophageal adeno and squamous cell carcinoma." (PMID 26878873, 2016). "We demonstrated that STMN1 expression associated with old age group, advanced T stage, the presence of lymph node metastasis, and a shorter disease-specific survival time in diffuse type gastric adenocarcinoma." (PMID 22470493, 2012). "In diffuse type gastric adenocarcinoma, STMN1 expression was associated with old age (p = 0.043), T stage (p = 0.004) and the presence of lymph node metastasis (p = 0.046)." (PMID 22470493, 2012). "In colon cancer patients, STMN1 expression is significantly related to lymph node metastasis and TNM staging." (PMID 33201835, 2020). "In diffuse type gastric adenocarcinomas, STMN1 expression was correlated with age (p = 0.043), T stage (p = 0.004) and lymph node metastasis (p = 0.046)." (PMID 22470493, 2012). "In addition, STMN1 and HER2 overexpression identifies high-risk patients and lymph node metastasis in endometrial cancer." (PMID 29079795, 2017). "Recently some reports showed that stathmin-1 is related to lymph node metastasis either." (PMID 24040910, 2013). "For patients with early ESCC, several biomarkers, including PTEN, STMN1, and TNFAIP8, were screened and showed a good ability to predict lymph node metastasis after surgery." (PMID 35903713, 2022). "To investigate the prognostic significance of STMN1 expression based on different clinical pathological characteristics, we performed subgroup analysis in patients with different TNM stage, depth of tumor invasion, lymph node metastasis and tumor differentiation, respectively." (PMID 29312550, 2017).
bladder cancer (8 papers, 2015 to 2025). "Clearly, increased STMN-1 activity was observed in bladder cancer tissue, both in non-invasive and invasive tumours, as well as in BC metastases." (PMID 40507426, 2025). "In the available literature, individual information was found on the examined proteins—HAI-1, STMN-1 and TN-C—in bladder cancer." (PMID 40507426, 2025). "Regarding OP18, also termed oncoprotein 18 and stathmin-1, immunohistochemical analyses of human donors and studies in the bladder cancer cell line T24 indicated that over-expression of OP18 is related to malignant cell characteristics." (PMID 32614890, 2020). "Further studies targeting STMN1 and the mechanism of miR-221 regulation by TGFβ1 induction will provide promising and feasible options for the treatment and prevention of human bladder cancer." (PMID 25928257, 2015). "Our study demonstrated that miR-221 facilitated TGFβ1-induced EMT in human bladder cancer cells by targeting STMN1 and represented a promising therapeutic target in the process of metastasis." (PMID 25928257, 2015). "Our data further support this conclusion that upregulated miR-221 suppressed expression of STMN1 in bladder cancer cells, further promoted the progressive and metastatic potential of human bladder cancer." (PMID 25928257, 2015). "Taken together, our findings demonstrate for the first time that miR-221 can facilitate the TGFβ1-induced EMT process in human bladder cancer cells by suppressing STMN1." (PMID 25928257, 2015). "By employing the Dual Luciferase Reporter Assay System, we report for the first time that miR-221 suppressed STMN1 expression by targeting STMN1 3′UTR in bladder cancer." (PMID 25928257, 2015). "In this study, STMN1 was downregulated by TGFβ1 in bladder cancer." (PMID 25928257, 2015). "Therefore, miR-221 negatively regulates STMN1 expression in bladder cancer cells." (PMID 25928257, 2015). "CDCA3, ANLN, STMN1, and DHCR24 play important roles in cell proliferation and migration of bladder cancer." (PMID 39540204, 2024). "We used qRT-PCR and western blot to accurately measure the levels of miR-221, STMN1 and EMT markers in TGFβ1 induced EMT of bladder cancer cells." (PMID 25928257, 2015). "Different in terms of protein functions, such as Hepatocyte growth factor activator inhibitor type 1 (HAI-1), Stathmin 1 (STMN-1) and Tenascin C (TN-C), whose activity has been observed in various types of cancer, inspired us to study them in bladder cancer." (PMID 40507426, 2025).
nasopharyngeal carcinoma (8 papers, 2015 to 2025). A carcinoma arising from the nasopharyngeal epithelium. "The combination of paclitaxel treatment and silencing of stathmin 1 enhanced the tumoricidal effect compared with that of paclitaxel alone, and paclitaxel suppressed the expression of stathmin 1 in nasopharyngeal carcinoma." (PMID 37162289, 2023). "Again similarly, Wu and colleagues determined that combination paclitaxel and siRNA-mediated STMN1 silencing increased to tending of apoptosis in nasopharynx carcinoma cell lines." (PMID 37529254, 2022).
endometrial cancer (7 papers, 2015 to 2025). Primary or metastatic malignant neoplasm involving the endometrium (mucous membrane that lines the endometrial cavity). "He found that STMN1 promotes the growth and invasion of endometrial carcinoma by mediating the secretion and activation of MMP2 and MMP9 proteins." (PMID 35126478, 2022). "Reyes reported that high STMN1 expression was a marker for clinical outcome in endometrial cancer." (PMID 29113350, 2017). "In patients with endometrial cancer, stathmin 1 was identified as a biomarker for unfavorable survival, but paclitaxel treatment might improve the outcomes of patients with high levels of stathmin 1 expression." (PMID 37162289, 2023). "STMN1 is a prognostic marker for various types of cancer, such as breast and endometrial cancer, and has also been shown to be independent of other factors, such as age, menopausal status, nodal status, nuclear grade, tumor size, and ER, PR, and HER2 expression." (PMID 26087399, 2015).
Anxiety (6 papers, 2012 to 2025). Intense feelings of nervousness, tension, or panic often arise in response to interpersonal stresses. "Previous studies reported that Stmn1 genetic variants influence fear and anxiety as well as cognitive-affective processing." (PMID 40110371, 2025). "Further, downregulation of Stathmin-1 signaling associated with suicidal ideation severity in the present study is also implicated in fear and anxiety behaviors in animal studies." (PMID 37398042, 2023). "We have observed increases in the microtubule-associated protein stathmin 1 in the amygdala of blast-exposed animals months after exposure that is associated with increased anxiety." (PMID 32094584, 2021). "In humans, fear and anxiety as well as cognitive and affective control processing were shown to be associated with STMN1 polymorphisms." (PMID 31454951, 2019). "Unifactorial linear regression analysis disclosed that expression of STMN1 and p16INK4a varied linearly and directly with the anxiety scores, and that there was a trend for TERT (F = 4.30, R2 = 0.22, p = 0.05)." (PMID 23185405, 2012). "Expression of p16INK4a and STMN1 was directly correlated with anxiety scores in the depression group, and that of p16INK4a, STMN and TERT with the depression and anxiety scores in the combined sample (MDD plus controls)." (PMID 23185405, 2012). "There was a moderate to strong direct linear relationship between the depression and anxiety scores and the expression of STMN1, p16INK4a and TERT." (PMID 23185405, 2012). "In the MDD sample anxiety scores were strongly and directly correlated with the expression level of p16INK4a (0.71, p = 0.001), STMN1 (0.67; p = 0.003), and non-significantly with that of TERT (0.47; p = 0.056)." (PMID 23185405, 2012).
cervical carcinoma (6 papers, 2015 to 2025). A carcinoma arising from either the exocervical squamous epithelium or the endocervical glandular epithelium. "In addition, STMN1 overexpression has been associated with poor survival, cancer progression and treatment resistance in several types of cancers including head and neck, ovarian, breast and cervical carcinomas." (PMID 26466335, 2015). "The microarray dataset of mRNA and miRNA analysis revealed RhoB and STMN1 genes as potential targets for cervical cancer diagnosis and treatment." (PMID 33946372, 2021). "Western blot analysis confirmed that LYZ, ORM1, LYN, STMN1 significantly increased in cervical cancer, while LUM, BGN, KRT4 significantly decreased." (PMID 27690342, 2016). "We found that LYZ, ORM1, LYN and STMN1 significantly increased in cervical cancer samples." (PMID 27690342, 2016). "Studies have found that high concentrations of propofol enhance the cytotoxicity of paclitaxel against cervical cancer cells by down-regulating stathmin 1 expression, but clinical concentrations of propofol may not have this effect." (PMID 40309242, 2025). "However, 30 μM propofol did not affect the expression of β‐tubulin protein or stathmin 1 protein in cervical cancer cells." (PMID 37162289, 2023).
melanoma (6 papers, 2016 to 2024). A malignant, usually aggressive tumor composed of atypical, neoplastic melanocytes. "Another subpopulation expressing high levels of MKI67 and STMN1 was classified as Mac_Prolif (n = 2234), and found to be enriched in liver, melanoma, and ovary tumor samples." (PMID 38972873, 2024). "The expression levels of the identified target genes encoding CTGF, THBS1, STMN1, BCL9, RAC1 and MCL1 allowed discrimination between phenotypic groups of melanoma cell lines with high or low-invasive capacity, respectively." (PMID 30197759, 2018). "To date, STMN1 results also to be over-expressed across many human cancers, included cutaneous squamous cell carcinoma, a non melanoma skin cancer." (PMID 29545914, 2018). "We observed that ENO1, PARK7, NPM1 and STMN1 genes expression levels were higher in melanoma cells than in melanocytes and in normal fibroblasts." (PMID 29545914, 2018). "Stathmin 1 has also been reported to affect cell proliferation and migration capabilities of melanoma cells." (PMID 26878873, 2016). "Interestingly, STMN1 has been reported to be up-regulated during the progression of melanoma." (PMID 29545914, 2018). "STMN1 is a downstream effector of MAPK signaling via a miRNA-regulated mechanism and a potential oncogene in melanoma." (PMID 40144773, 2024). "Furthermore, Stathmin 1 (STMN1) was selected as it was found uniquely down-regulated in miR-193b transfected cells, and due to the fact that STMN1 represents a potential target for melanoma therapy." (PMID 30197759, 2018).
neuroblastoma (6 papers, 2012 to 2023). Neuroblastoma (NB) is the most common solid, extracranial childhood tumor. "High levels of STMN1 expression were associated with malignant potential, proliferation potency, and poor prognosis in neuroblastoma." (PMID 37760452, 2023). "This study found that high levels of STMN1 expression in neuroblastoma indicate malignant potential, proliferation potency, and poor prognosis." (PMID 37760452, 2023). "Functional analysis revealed the association among STMN1 suppression, cellular viability, and endogenous or exogenous MYCN expression in neuroblastoma cell lines." (PMID 37760452, 2023). "A study found that stathmin 1 suppression reduced neuroblastoma cell invasion into the extracellular matrix and that its role in tumor invasion is mediated by RHO-associated protein kinase (ROCK), a key regulator of cell migration." (PMID 36230740, 2022). "In neuroblastoma, STMN1 phosphorylation was reported to impact on metastasis by altering the levels of tyrosine-protein phosphatase non-receptor type 14 (PTPN14) or in a tubulin-independent manner to enhance transendothelial migration via RhoA/ROCK signaling." (PMID 34771457, 2021). "Knockdown of microtubule-destabilized protein Stathmin-1 reduced lung metastasis in an orthotopic neuroblastoma mouse model." (PMID 30874545, 2019). "STMN1 has been found to be overexpressed in neuroblastoma and is upregulated in vincristine-resistant neuroblastoma cells." (PMID 25897432, 2015). "Using immunohistochemical staining, STMN1 expression was examined in 81 neuroblastoma samples." (PMID 37760452, 2023). "STMN1 expression was an independent prognostic factor in patients with neuroblastoma." (PMID 37760452, 2023). "The study suggests that assessing STMN1 expression could be a powerful indicator of prognosis and a promising therapeutic candidate against refractory neuroblastoma." (PMID 37760452, 2023). "Thus, the role of stathmin 1 in neuroblastoma tumorigenesis makes it a potential target for cancer therapeutics." (PMID 36230740, 2022). "Finally, stathmin 1 suppression in neuroblastoma tumor models decreased whole-body metastasis in the lung, kidney, and liver." (PMID 36230740, 2022). "Moreover, reduced stathmin 1 expression in neuroblastoma cells significantly increased the activity of transforming protein RhoA, which is upstream of ROCK, and induced expression of the RhoA/ROCK pathway." (PMID 36230740, 2022). "Of the 91 NB-suspected specimens, the ratio of positive STMN1 expression was higher in NB (23.5%, 19/81 cases) than in ganglioneuroma (0%, 0/9 cases), ganglioneuroblastoma (0%, 0/1 case), and surrounding non-tumoral tissues." (PMID 37760452, 2023). "Uncovering the differential phosphorylation of LMNA and STMN1 upon NTRK1 activation gives new clues on NTRK1-mediated regulation of the differentiation and proliferation of neuroblastoma cells." (PMID 34771457, 2021). "Furthermore, STMN1 knockdown inhibited neuroblastoma cell growth regardless of endogenous and exogenous MYCN overexpression." (PMID 37760452, 2023). "Our data suggest that assessing STMN1 expression in neuroblastoma could be a powerful indicator of prognosis and that STMN1 might be a promising therapeutic candidate against refractory neuroblastoma with and without MYCN amplification." (PMID 37760452, 2023). "STMN1 knockdown inhibited neuroblastoma cell growth regardless of MYCN overexpression." (PMID 37760452, 2023). "Therefore, this study aimed to assess the clinical significance and STMN1 function in neuroblastoma with and without MYCN amplification." (PMID 37760452, 2023).